MYC (MYC proto-oncogene, bHLH transcription factor)
Diseases named in the same sentence as MYC in open-access papers (continued):
Sharing a sentence is not in itself a finding about the gene and the disease.
cancer (continued). "Our findings support a direct link between MYC and cancer cell viability, and raise the possibility that inactivation of MYC may be an effective therapeutic strategy for KRAS mutant tumors across various cancer types." (PMID 28152508, 2017). "MYC is a critical growth regulatory gene that is commonly overexpressed in a wide range of cancers." (PMID 28362357, 2017). "Moreover, we show that MYC modulation in heterotypic co-cultures of human cancer cells is sufficient as to subvert their competitive state, regardless of genetic heterogeneity." (PMID 28974715, 2017). "Thus, knowledge of MYC-driven networks in breast cancer progression will expand our range of pharmacological inhibitors that can kill cancer cells with precision and efficacy." (PMID 28696357, 2017). "Thus, our interest in this payload class extends beyond its excellent potency against quiescent and MDR expressing cancer cell lines due to its potential therapeutic benefits against the MYC-driven cancers." (PMID 28558059, 2017). "MYC has been shown to regulate glutamine metabolism in multiple cancer cell types." (PMID 28696357, 2017). "Interestingly, the MYC module was also found to be highly expressed in cancer cells and to be predictive of cancer outcomes, emphasizing the potential therapeutic implications of unraveling the MYC-mediated regulatory circuitry in PSCs." (PMID 28217689, 2017). "All these features indicate that c‐MYC behaves as a cancer driver gene for PDAC." (PMID 28275007, 2017). "In addition, c-MYC expression is physiologically induced during G1/S-phase progression and deregulated in a variety of malignant tumors." (PMID 28977920, 2017). "Altogether, our findings suggest that changes in MYC activity during cancer progression may drive competitive clonal selection downstream of genetic heterogeneity." (PMID 28974715, 2017). "In recent years, these two intrinsic features of the MYC protein were shown to merge in a unique trait named “cell competition”, an evolutionarily conserved mechanism ultimately governing cell selection in organ development and, possibly, in cancer." (PMID 28420161, 2017). "MYC is elevated in TNBC compared with other cancer subtypes." (PMID 28696357, 2017). "Hence, targeting p300 can be effective but it seems to be context-dependent and further studies are needed to unravel the full possibilities of p300 inhibitors in MYC-positive cancers as well as their translation into the clinical setting." (PMID 28505071, 2017). "Thus, on the basis of the observed exon-specific effect of Tz 1, we can conclude that Tz 1 binds and stabilizes the G-quadruplex structure in c-MYC P1 promoter and specifically reduces c-MYC expression in cancer cells." (PMID 28706243, 2017). "MYC activation is considered a hallmark of cancer initiation and maintenance, and the discovery of MYC function in CC has primed a series of speculations about a possible role for this phenomenon in cancer." (PMID 28420161, 2017). "The MYC oncogene is a transcription factor that has a broad effect on gene expression: it regulates more than 15% of human genes, including a number of microRNA (miRNAs), and contributes to the pathogenesis of many human cancers." (PMID 28212447, 2017). "MYC is highly expressed in most cancer cells, including HT1080 cells." (PMID 28474697, 2017). "The impact of miR-193a-mediated interruption of the caprin-1/G3BP-1/c-MYC/Cyclin D2 complex could be a potential target for anti-cancer therapeutic applications." (PMID 28211508, 2017). "Dysregulated MYC proteins cannot alone drive and promote cancer." (PMID 28333115, 2017). "Our findings suggest that combined targeting of MYC and Menin signalling might serve as an effective therapeutic strategy in cancer cells with aberrant expression of these oncoproteins." (PMID 28474697, 2017). "Interestingly, PVT1 is found co-amplified with MYC in a high percentage of cancers carrying an amplification of the chromosomal region 8q24.21." (PMID 28704924, 2017).
cancer (continued). "Moreover, they are highly associated with cancer metastasis and the expression of oncogenic factors (KRAS proto-oncogene GTPase, MYC, and MDR1)." (PMID 28798901, 2017). "While in most non-malignant cells MYC levels are low, its constitutive expression is linked to the pathogenesis of many human cancers." (PMID 29100357, 2017). "Thus, interfering with the RSR pathway per se prohibits cancer formation at least in MYC driven malignancies in mice." (PMID 29167438, 2017). "Accordingly, an elevated or deregulated level of MYC is a hallmark of the vast majority of human malignancies and is usually recognized as a poor prognostic marker, indicating a strong link between deregulation or overexpression of the MYC gene and advanced cancer development." (PMID 28590415, 2017). "In addition, MYC plays critical roles in multiple cellular pathways that promotes survival of cancer cells." (PMID 28696357, 2017). "The expression of oncogene MYC was much higher in tamoxifen resistant cell line, and it might contribute to the unlimited proliferation of cancer cells." (PMID 28415819, 2017). "The c-MYC proto-oncogene (referred to throughout as MYC) is a well-known driver of cancers." (PMID 28362357, 2017). "Therefore, as both a downstream target of metabolism and an upstream regulator, MYC is a prominent central regulator of cancer metabolism." (PMID 28362357, 2017). "Since the MYC gene family is activated in nearly 70% of all human cancers, targeting myc-driven processes could have broad applications." (PMID 29215586, 2017). "In this cancer type, also c-MYC amplification co-occurred with RPL5 inactivation." (PMID 28147343, 2017). "In this article, we review MYC’s function as a regulator of the cancer epigenome and transcriptome." (PMID 28505071, 2017). "In sum, our metabolic and transcriptomic analyses have revealed that depletion or inhibition of CDK4/6 in cancer cells leads to de novo addiction to MYC, and, as likely downstream consequences, also to glutaminase and mTOR signaling, as well as to a compromised adaptation to hypoxia." (PMID 28978620, 2017). "Moreover, the expression level of MYC was found to be relatively high in CSCs derived from several cancer types when compared to bulk cell populations." (PMID 27821172, 2016). "The MYC and related MYCN oncogenes (encoding MYC and N-MYC) are translocated, amplified, or mutated in many cancers, and can dramatically upregulate genes involved in glucose and glutamine metabolism, ribosomal, lipid, and nucleotide biogenesis, and cell cycle progression." (PMID 27500134, 2016). "MYC is known to play important roles in proliferation and survival of many cancer cells." (PMID 26925584, 2016). "Overexpression of the c-MYC oncogene occurs in most human cancers." (PMID 27590350, 2016). "Furthermore, MYCN-promoted SGO1 transcription and SGO1 expression tended to be higher in MYCN- or MYC-overexpressing cancers." (PMID 27539729, 2016). "Activation of MYC pathway has been shown in diverse cancers." (PMID 27294413, 2016). "Recently, MYC has been reported to induce accumulation of DNA oxidative adducts and impair cell cycle regulatory capacity which potentially can increase the genomic instability and provide an environment conducive to growth of the cancer cells." (PMID 26919708, 2016). "Regardless, we believe that the growth inhibitory effects of the Pu27 family of oligonucleotides may provide an opportunity to effectively target c-MYC expression that could be exploited for cancer therapy." (PMID 27551915, 2016). "The MYC proto-oncogene is over-expressed in a large portion of human cancers." (PMID 27382434, 2016). "Therefore, the increases in MYC production observed in cancer cells can alter the transcription of some genes more than others." (PMID 27460973, 2016). "MYC expression is significantly elevated in almost all cancers including HCC and GBM." (PMID 27409345, 2016).
cancer (continued). "The proto-oncogene MYC is one of several well-known transcription factors involved in the genesis and progression of many types of cancer acting as a main regulator of the expression of genes involved in cell proliferation, invasion, apoptosis, metabolism, DNA repair and protein synthesis." (PMID 27014720, 2016). "Hence, cancer metabolism appears to be adapted to the anabolic program, which is under direct management by various oncogenes, such as MYC and hypoxia-inducible factor 1 (HIF-1)." (PMID 27447861, 2016). "c-MYC and other master factors have been observed to be abnormally expressed in many cancers." (PMID 27092944, 2016). "Human cancers frequently arise from increased expression of proto-oncogenes, such as MYC and HER2." (PMID 27382434, 2016). "In this review, we summarize the current understanding of the reprogramming of cancer metabolism via the counterbalance between MYC and HIF-1, and discuss the proven and putative roles of the NDRG family in adjusting cancer metabolism according to the ambient oxygen level." (PMID 27447861, 2016). "Moreover, dual deficiency of oxygen and glucose suppresses HIF signaling and enhances MYC degradation in cancer cells as an adaptive response to survive under conditions of deficient energy sources." (PMID 28040803, 2016). "We propose that further analysis of mechanisms of MYC silencing in spermatogonial progenitors may reveal novel fundamental information relevant to understanding of MYC expression in cancer." (PMID 29527532, 2016). "Its role in the stromal compartment is not to our knowledge known, but potentially BASP1 modulation may impact a host of MYC-dependent processes in the cancer microenvironment." (PMID 26934553, 2016). "The most well-characterised member of the family, MYC, is frequently deregulated in adult cancers." (PMID 27448979, 2016). "Moreover, inhibitors of BET binding can disrupt the growth of cancer cells and this phenomenon has been attributed to the sensitivity of super-enhancers, driving oncogenes such as MYC and BCL2, to BET disruption." (PMID 27097319, 2016). "c-MYC is thus viewed as a promising target for anti-cancer drugs." (PMID 27827996, 2016). "Accordingly, four amino acid transporters (SLC1A5, SLC7A5, SLC7A11 and SLC6A14) have been found to be overexpressed in cancer cells in a MYC-dependent manner or through miR-23a repression mediated by MYC to increase the uptake of amino acids and meet their growing demands." (PMID 28040803, 2016). "Importantly, c-MYC is an established oncogene and its aberrant activation occurs in many human cancers." (PMID 26871295, 2016). "However, longer incubation of WHCO1 and MDA MB 231 cells with WJ-MSCs did not result in sustained downregulation of PCNA, BCL-2, MMP-2, and c-MYC gene expression in the cancer cells indicating that the effect of coculture is transient." (PMID 26880967, 2016). "Indeed, a recent global UK-American initiative to develop therapies against cancer had listed as one area of research to be the inhibition of c-MYC." (PMID 27259258, 2016). "It remains to be determined in what contexts overexpressed MYC in cancer deregulates clock genes through either promoter co-occupancy, competition with CLOCK-BMAL1 to trasactivate or repress target genes, or through forming novel complexes with either CLOCK or BMAL1." (PMID 27500134, 2016). "Nevertheless, numerous strategies have been employed to target MYC at various stages of biological and pathological development, and there have been significant advances in understanding the MYC dependence of cancer and developing novel approaches to targeting MYC activity in the past five years." (PMID 27081479, 2016). "Based on these findings, PET imaging may be further studied as a biomarker that identifies patients with NB or other cancers who would most likely to benefit from novel therapies targeting MYC/MYCN or the glycolytic pathway." (PMID 26959748, 2016).
cancer (continued). "In addition, amplified and AR-regulated genes showed enrichment in MTORC1 signaling, DNA replication, cell cycle, MYC targets, mismatch repair, homologous recombination, nucleotide excision repair, epigenetic regulators, and pathways in cancer." (PMID 27623747, 2016). "First, we analysed the expression of BPTF and c-MYC in the Cancer Cell Line Encyclopedia data set." (PMID 26729287, 2016). "Both the ERK1/2 and MYC networks play key roles in cancer development." (PMID 27557521, 2016). "The ability of MYC to stimulate ribosome biogenesis is critical for the orchestration of the processes of cell cycling and energy production required for proliferation of cancer cells." (PMID 27588501, 2016). "Knock-down of MYC in cancer cell lines can induce cell death." (PMID 27382434, 2016). "Many efforts have been made to deliberately target MYC for cancer therapy." (PMID 27081479, 2016). "Owing to this critical role of c-MYC in cancer, understanding the mechanisms that regulate c-MYC protein expression may lead to new therapeutic opportunities." (PMID 27253416, 2016). "In addition, we found that SGO1 is a transcriptional target of MYCN, and that SGO1 expression correlates with MYCN or MYC expression in various cancers." (PMID 27539729, 2016). "Further understanding of the details of MYC regulation by E1A 1-80 may be valuable for cancer therapeutics targeting MYC." (PMID 27382434, 2016). "The MYC (or c-myc) protooncogene is a regulator gene that encodes for a transcription factor and plays a central role in regulating cell cycle proliferation, neoplastic transformation, and apoptosis and MYC abnormalities have been found in many cancers including CCA." (PMID 27127503, 2016). "Inhibition of MYC is an attractive pharmacological approach for cancer treatment." (PMID 27366943, 2016). "Notably, the global protein glycosylation level has been reported being increased upon c-MYC activation and elevated in cancer cells." (PMID 27655693, 2016). "The proclivity of c-MYC-polyploidy associated genes towards cancer contradicts the absence of active proliferation, genome instability, and cancer in these normal tissues." (PMID 27655693, 2016). "MYC is documented to be deregulated in up to 70% of human cancers." (PMID 27684546, 2016). "Ultimately, it may be necessary to strategically target MYC from a multitude of angles, taking advantage of its well-established role as a master regulator of transcription in cancer cells." (PMID 27081479, 2016). "Over expressions of several abnormal/mutated growth factors (e.g., MYC, PI3K, MAPK, erythropoietin receptor-B cell factor-1-EBCR1 or BCR) that are also known to contribute to the multistep carcinogenesis in adult cancers are reported in childhood cancers." (PMID 27558401, 2016). "Indeed, a marked increase in rRNA synthesis is a general attribute of many cancers and rRNA transcription was shown to be stimulated by c-MYC." (PMID 27198694, 2016). "Moreover, MYC amplification stimulates E2F expression in cancer cells, facilitating the commitment to cell division." (PMID 27234232, 2016). "Indeed, ZMYND11 depletion caused up-regulation of MYC, and enhanced proliferation in cancer cells and mutations of ZMYND11 were identified in several cancers." (PMID 27631103, 2016). "Another study identified CSNK1e (protein CK1ε) as a synthetic lethal target of MYC and N-MYC upregulated in neuroblastoma and other human cancers, and upregulation of CK1ε would be expected to destabilize the clock through its promotion of PER degradation and activation of BMAL1." (PMID 27500134, 2016). "Dissecting the pathways required by cancer cells to tolerate oncogenic stress imposed by activated MYC potentially allows identification of druggable targets that would lead to a more specific and less toxic therapeutic treatments for MYC-driven tumors." (PMID 25477524, 2015).
cancer (continued). "In addition, pan-aurora kinase inhibitors, VX-680 and CCT137690 which also target AURKB, were reported to sensitize cancer cells with high expression of MYC and MYCN." (PMID 26497213, 2015). "In some cancers, MYC amplification is involved in glutamine addiction." (PMID 26402672, 2015). "Our data suggest that controlling the activity of SIRT3 might be an alternative approach to manage c-MYC in cancer cells." (PMID 26317998, 2015). "The example of MYC amplification shows that only small parts of a cancer may harbor such alterations, and that MYC amplification may be present only in as little as two of the nine analyzed cancer regions." (PMID 25649416, 2015). "Targeting MYC oncogene and metabolic signaling partners offers new anti-cancer therapeutics." (PMID 26398947, 2015). "The MYC family of proto-oncogenes (MYC, MYCN, and MYCL) has been broadly implicated in cancer." (PMID 26029667, 2015). "Nevertheless, our results demonstrating the identification of FBXW7 as a synthetic lethal target in the context of MCF10A-MYCER adds insight to the still enigmatic role of the interaction between FBXW7 and MYC in human cancer initiation, progression, and maintenance." (PMID 25669969, 2015). "In addition, the master regulator of the cellular anti-oxidant response Nrf2 can be activated and stabilized by a number of oncogenes, for example PI3K, K-ras or MYC, known to drive signaling cascades that mediate cancer cell proliferation and/or survival." (PMID 26369938, 2015). "MYC is frequently amplified and/or overexpressed in various types of cancer." (PMID 26003165, 2015). "MYC induces cancer cell proliferation through cell cycle regulation." (PMID 26003165, 2015). "In addition, HUWE1 has also been shown to be required for the promotion of cell survival and tumorigenesis, through the K63-linkage ubiquitination of c-MYC and hence its activation in cancer cells." (PMID 25883150, 2015). "In this study, copy number gains of MYC were found at a high prevalence in the intestinal-type cancers as compared to the diffuse-type cancers, supporting the observation that MYC protein expression is more frequently observed in intestinal-type tumors than in diffuse-type tumors." (PMID 26360582, 2015). "Because accelerated cell division imposed by activated MYC is associated with increased risk of replication errors and DNA damage, it is reasonable to postulate that cancer cells with activated MYC are particularly sensitive to reduced RecQ helicases such as BLM and WRN (59, –, 62)." (PMID 25477524, 2015). "We noticed that miR-145 is the most widely studied miRNA in cancer, especially in PC, and our analysis showed that it could inhibit the expression of c-MYC and CDKNIA, which play important roles in CRPC." (PMID 26540468, 2015). "In the future, it will be important to determine how universal these lncRNAs are to the functions of MYC and whether a similar regulation of MYCLos by MYC is observed in other cancers." (PMID 27077133, 2015). "Thus, both studies suggest that a therapeutic window for splicing inhibition exists in MYC-driven cancers." (PMID 26490253, 2015). "Studies have shown that many malignant tumors have over-expressed MYC and under-expressed MAX." (PMID 26046465, 2015). "Intriguingly, this may influence the bioenergetics of MYC amplified tumors and therefore confer a powerful growth advantage necessary for the evolution and metastasis of this aggressive cancer." (PMID 25970789, 2015). "Through careful review, we summarized their function and action together and found that a novel MYC-centered pathway was hidden under the crosstalk subnetwork, which may play important roles in metformin action in T2D and cancer." (PMID 26083494, 2015). "Indeed, the ubiquitination level of c-MYC protein was increased in SIRT3 overexpressed cancer cells." (PMID 26317998, 2015). "In addition, c-MYC protein level was restored when cancer cells were treated with proteasome inhibitor MG132." (PMID 26317998, 2015).